PDE6H (phosphodiesterase 6H)
Description:
Participates in processes of transmission and amplification of the visual signal. cGMP-PDEs are the effector molecules in G-protein-mediated phototransduction in vertebrate rods and cones.
Synonyms: ACHM6; RCD3
Tractability: Small molecule: an approved drug acts on it; a high-quality ligand is known; it belongs to a druggable protein family. PROTAC: a small molecule that binds it is known.
Gene: Protein-coding gene on chromosome 12 (14,973,042 to 14,981,865, forward strand). Ensembl gene ENSG00000139053.
Subcellular location (Human Protein Atlas): Vesicles
Gene Ontology:
Molecular function: protein binding; enzyme inhibitor activity; 3',5'-cyclic-GMP phosphodiesterase activity; 3',5'-cyclic-nucleotide phosphodiesterase activity; cGMP binding
Biological process: visual perception; positive regulation of epidermal growth factor receptor signaling pathway; positive regulation of G protein-coupled receptor signaling pathway; transducin-mediated opsin signaling pathway
Cellular component: cone photoreceptor disc membrane; membrane protein complex; photoreceptor outer segment membrane
Genetic constraint (gnomAD): Loss-of-function variants: 5 observed, 3.9 expected, observed/expected ratio (o/e) 1.28, 90% interval 0.63 to 1.9. That is too few expected variants to judge how well the gene tolerates losing a copy. Missense variants: 51 observed, 57.65 expected, observed/expected ratio (o/e) 0.88, 90% interval 0.71 to 1.12. Synonymous variants: 16 observed, 18.63 expected, observed/expected ratio (o/e) 0.86, 90% interval 0.58 to 1.3.
Homologues: Orthologues: chimpanzee PDE6H (98% identical), pig PDE6H (96% identical), guinea pig PDE6H (95% identical), rabbit PDE6H (93% identical), mouse Pde6h (92% identical), tropical clawed frog pde6h (84% identical), dog PDE6H (69% identical), macaque PDE6H (67% identical), rat Pde6h (51% identical). Paralogues in human: PDE6G (82% identical).
Diseases named in the same sentence as PDE6H in open-access papers:
PDE6H is named in the same sentence as 23 diseases in open-access papers, as found by Europe PMC text mining. Sharing a sentence is not in itself a finding about the gene and the disease. The quoted sentences say what the papers report.
achromatopsia (11 papers, 2016 to 2025). Achromatopsia (ACHM) is a rare autosomal recessive retinal disorder characterized by color blindness, nystagmus, photophobia, and severely reduced visual acuity due to the absence or impairment of cone function. "Biallelic pathogenic mutations in PDE6H are associated with achromatopsia, with ocular symptoms such as diminished visual acuity (VA) and photophobia (sensitivity to light) and abnormal colour vision." (PMID 41153400, 2025). "Andersen and colleagues conducted a study of Danish achromatopsia patients and compared refractive error across causal genes, including PDE6H." (PMID 41153400, 2025). "A particular nonsense variant in PDE6H has been reported homozygously as a rare cause of incomplete achromatopsia, although a case of complete achromatopsia has also been reported in association with the same variant." (PMID 40013354, 2025). "A later study (and the current report) supported a unique genotype–phenotype correlation related to KCNV2 variants, and PDE6H variants are now considered a rare cause of achromatopsia." (PMID 33309813, 2021). "However, this phenotype (or lack thereof) differs from that in human patients with incomplete achromatopsia due to the loss-of-function mutation in the PDE6H gene." (PMID 38110033, 2024). "This is the second report of a homozygous PDE6H:c.35C>G variant causing incomplete achromatopsia (OMIM 610024), thus strongly supporting the hypothesis that loss-of-function variants in PDE6H cause this visual deficiency phenotype." (PMID 27472364, 2016). "The similar clinical presentation between familial achromatopsia in humans and bovine recessive day-blindness led to the hypothesis that a protein-changing variant within CNGA3, CNGB3, GNAT2, ATF6, PDE6C, and PDE6H would be associated with achromatopsia of Original Braunvieh calves." (PMID 34830323, 2021). "Refractive errors in patients with achromatopsia appear to be gene-specific, where biallelic pathogenic variants in PDE6C and PDE6H tend to be associated with myopia." (PMID 41153400, 2025). "We identified variants believed to be disease causing in five of the known achromatopsia genes: CNGA3; CNGB3; GNAT2; PDE6C and PDE6H; and novel variants were identified in CNGB3 and PDE6C." (PMID 36980963, 2023). "Pathogenic variants in six genes (CNGA3, CNGB3, GNAT2, ATF6, PDE6C, and PDE6H) have been identified in humans with achromatopsia (OMIM 216900)." (PMID 34830323, 2021). "Achromatopsia is caused by sequence variants in CNGA3, CNGB3, GNAT2, PDE6H, PDE6C, and ATF6." (PMID 39273686, 2024). "Pathogenic variants in different genes such as CNGA3, CNGB3, GNAT2, PDE6H, ATF6 and PDE6C have been reported to be relevant to COD, cone-rod dystrophy (CORD) and achromatopsia (ACHM) diseases." (PMID 38956522, 2024).
breast carcinoma (3 papers, 2013 to 2025). "We determined the effect of knockdown of PDE6H on HCT116 cells, a breast cancer cell line (MDA-MB-436), and a non-small cell lung cancer cell line (NCI-H23) all cultured at 5-mM glucose (the physiological concentration)." (PMID 38350962, 2024).
retinal dystrophies (3 papers, 2023 to 2024). "Concurrently, PDE6H’s pivotal role in phototransduction processes within retinal photoreceptor cells has been elucidated, with mutations in PDE6H linked to retinitis pigmentosa, a genetic retinal dystrophy." (PMID 38605967, 2024). "This explains why pathogenic variants in PDE6A (OMIM #180071), PDE6B (OMIM #180072) and PDE6G (OMIM #180073) cause predominantly rod-involving retinal dystrophies, whereas pathogenic variants in PDE6C and PDE6H (OMIM #600827 and #601190) lead to retinal dystrophies which predominantly affect cones." (PMID 37433860, 2023).
cone-rod dystrophy (2 papers, 2020 to 2024). Inherited retinal dystrophies that belong to the group of pigmentary retinopathies. "In contrast, PDE6H, a cone-rod dystrophy gene, demonstrated preferential expression in peripheral rods." (PMID 32555229, 2020).
myopia (2 papers, 2023 to 2025). "Studies have also investigated the possibility of an association of PDE6H with high myopia." (PMID 41153400, 2025). "One study examined 50 patients with high myopia, and genetic testing determined that 4 of the patients had mutations linked with retinal dystrophies (GUCY2D, FAM161A, PDE6H, CACNA1F), suggesting an association between GUCY2D and high myopia." (PMID 41153400, 2025).
age-related macular degeneration (1 paper, 2024). Age-related loss of vision in the central portion of the retina (macula), secondary to retinal degeneration. "The focus on PDE4B and PDE6H in relation to ocular diseases has intensified, with research indicating PDE4B’s dysregulation in conditions such as glaucoma, diabetic retinopathy, and age-related macular degeneration (AMD), positing it as a promising therapeutic target." (PMID 38605967, 2024).
retinal degeneration (1 paper, 2014). Degeneration of the retina. "Group (b) was very small with only 9 genes, and it did not make a cluster of functionally related GO terms, although 6 of 9 genes were annotated as causal genes for retinal degeneration (Abca4, Elovl2, Fscn2, Nxnl1, Pde6c, and Pde6h)." (PMID 24747725, 2014).
visual disorders (1 paper, 2024). "Overall, a better understanding of the mechanism of PDE6 maturation and the roles of AIPL1 and Pγ will help to design therapeutic strategies to treat visual disorders linked to mutations in the AIPL1, PDE6G, and PDE6H genes." (PMID 38110033, 2024).
cancer (2 papers, 2024 to 2025). A tumor composed of atypical neoplastic, often pleomorphic cells that invade other tissues. "Role of PDE6H in cancer cell growth and metabolism was studied through the effects of its depletion on levels of cell cycle controllers, mTOR effectors, metabolite levels, and metabolic energy assays." (PMID 38350962, 2024). "We show that in HCT116, PDE6H deletion replicates many effects of the dark retina response and identify PDE6H as a new target in preventing cancer cell proliferation and tumour growth." (PMID 38350962, 2024). "PDE6H knockdown induced G1 cell cycle arrest and cell death and reduced mTORC1 signalling in cancer cell lines." (PMID 38350962, 2024). "The effect of inhibition cGMP-specific PDE on cellular metabolism and the G1 arrest inducing results of PDE6H knockdown in HCT116 brought to our attention PDE6H as a controller of cancer cell proliferation and metabolism." (PMID 38350962, 2024). "In this study, we demonstrate that PDE6H plays an essential role in regulating proliferation and metabolism in several cancer cell lines that represent a range of tumour types." (PMID 38350962, 2024). "Here, we define a role for photoreceptor cone gene PDE6H in regulating cancer cell proliferation and metabolism." (PMID 38350962, 2024). "Moreover, PDE6H, the inhibitory (or gamma) subunit of the cone-specific cGMP phosphodiesterase, has been identified as a key controller of cancer cell growth." (PMID 41179677, 2025). "PDE6H mRNA is also overexpressed in renal carcinoma (chromophobe renal cell and renal pelvis urothelial carcinomas), prostate carcinoma, and breast (ductal in situ) cancer cells, compared to normal tissue." (PMID 38350962, 2024). "The purpose of this study is to characterise the role of PDE6H in cancer cell growth." (PMID 38350962, 2024). "The relation of PDE6H, a significant target of this screen, to cancer was unknown." (PMID 38350962, 2024). "-PDE6 plays an oncogenic role in several cancers by disrupting cyclic nucleotide signaling, Wnt5a-Frizzled-2 pathway, and ERK activation-PDE6H knockout suppresses mTORC1 signaling and mitochondrial function, and induces cell cycle arrest." (PMID 41179677, 2025). "However, since the mechanistic effects of PDE6H in non-retinal cells are poorly understood and because of its identification via the screen, we investigated the pathways it acts through in cancer cell lines." (PMID 38350962, 2024).
tumor (2 papers, 2024). "Sildenafil was expected to have effects on stroma and vessels, whereas the effects of PDE6H depletion would be confined to tumour cells in KO tumours." (PMID 38350962, 2024). "Immunohistochemistry (IHC) analysis showed that the glycogen content of PDE6H KO HCT116 tumours was lower than those of mock HCT116 tumours." (PMID 38350962, 2024). "Among the identified RB tumor marker genes are known RB markers like the immature precursor gene CRX as well as genes of mature photoreceptors including phosphodiesterase 6H (PDE6AH) and arrestin 3 (ARR3), specific for cones." (PMID 39695086, 2024). "PDE6H knockout and sildenafil treatment slowed tumour growth and improved survival." (PMID 38350962, 2024). "Despite this, the effects of sildenafil treatment and PDE6H knockout on tumour growth were similar." (PMID 38350962, 2024). "Effect of PDE6H deletion on tumour growth was also studied in a xenograft model." (PMID 38350962, 2024). "HCT116 xenografts revealed that PDE6H deletion, as well as treatment with the PDE5/6 inhibitor sildenafil, slowed down tumour growth and improved survival, while sildenafil treatment did not have an additive effect on slowing the growth of PDE6γ′-deficient tumours." (PMID 38350962, 2024). "In xenografts, CRISPR-Cas9 mock control and PDE6H KO HCT116 were treated with vehicle (corn oil) or 150 mg/kg sildenafil citrate, starting the day the tumour size reached 50 mm3." (PMID 38350962, 2024). "Since PDE6H depletion inhibited proliferation as well as disrupting spheroid growth, we investigated the effects of PDE6H knockout and PDE6 inhibition on tumour growth in vivo." (PMID 38350962, 2024). "Ki-67, glycogen content, and vessel area were lower in PDE6H KO HCT116 tumours with (D) and without (C) sildenafil treatment." (PMID 38350962, 2024). "The systemic effects of sildenafil treatment being less pronounced in PDE6H KO tumours might help explain why tumour growth is similar in these tumours with or without sildenafil treatment." (PMID 38350962, 2024).
PDE6H also shares sentences with these, for which no sentence is quoted: retinoblastoma (2 papers); alopecia (1); Blindness (1); breast tumor (1); cone dystrophy (1); diabetic retinopathy (1); glaucoma (1); Macrocephaly (1); non-small cell lung carcinoma (1); Obesity (1); Retinal atrophy (1); retinal diseases (1); retinitis pigmentosa (1).